GAS6 (growth arrest specific 6)
Diseases named in the same sentence as GAS6 in open-access papers (continued):
Sharing a sentence is not in itself a finding about the gene and the disease.
ovarian carcinoma (continued). "When AXL is complexed with its ligand GAS6 in ovarian cancer cells, OPCML chaperones the AXL-GAS6 complex into external membrane lipid-raft domains where the complex becomes dephosphorylated through apposition to a raft restricted phosphatase and then targeted for ubiquitin-dependent degradation." (PMID 40699804, 2025). "In mesenchymal subtype ovarian cancer cell lines, crosstalk between GAS6 activation of AXL and receptor tyrosine kinases (HER2 and MET) and its downstream signalling served specifically to enable cell mobility in mesenchymal cells, a feature absent from other molecular subtypes." (PMID 40696160, 2025). "The GAS6-AXL signaling pathway is another crucial player in drug resistance in ovarian cancer." (PMID 38539161, 2024). "The growth arrest-specific protein 6 (GAS6) – AXL tyrosine kinase (AXL) interaction, for example, which are both associated with poor outcome, have already been evaluated in clinical trials in ovarian cancer by inhibiting their interaction." (PMID 39669575, 2024). "Furthermore, Gas6 expression is upregulated in a variety of cancer cells, including ovarian cancer, glioma, and melanoma cell lines." (PMID 39451556, 2024). "Importantly, siRNA-mediated inactivation of AXL was also sufficient to block the internalization of GAS6 in ovarian cancer SKOV3 cells that express all three TAM receptors." (PMID 35622156, 2022). "LINC00565 promotes ovarian cancer development by interacting with GAS6 as an oncogene." (PMID 34906173, 2021). "The level of Gas6 was shown to be elevated in ovarian cancer patients." (PMID 32385243, 2020). "For this reason, an anti-GAS6 antibody may be employed as a useful adjunct therapy for ovarian cancer." (PMID 23878800, 2013). "Therefore, from a therapeutic point of view, more robust studies on the function of GAS6 in ovarian cancer are required." (PMID 23878800, 2013). "Based on the weighted average (WA) method of scoring, GAS6 expression was stronger in epithelial ovarian cancers (EOC; n = 172) and ovarian borderline tumours (OBL; n = 40) than in ovarian surface epithelium (OSE; n = 6) or normal fallopian tubes (Tube; n = 3) (P = 4.97 × 10−5)." (PMID 23878800, 2013). "Strong cytoplasmic staining of GAS6 was observed in epithelial ovarian cancer tissues." (PMID 23878800, 2013). "If the GAS6/AXL axis is also involved in chemoresistance in ovarian cancer, targeting this pathway may sensitise tumours to paclitaxel and carboplatin, the current mainstays of therapy, whilst also directly inhibiting tumour growth." (PMID 23878800, 2013). "GAS6 is overexpressed in various cancers including ovarian cancer." (PMID 23878800, 2013). "However, functional studies of GAS6 in ovarian cancer were beyond the scope of our study, but earlier studies have shown that GAS6 is a member of the vitamin K-dependent protein family." (PMID 23878800, 2013). "Co-overexpression of AXL with Gas6 has also been reported in several types of tumors including ovarian cancer, and may therefore have an important role in uncontrolled cell growth/proliferation." (PMID 19055724, 2008). "Next, we assessed whether Gas6 stimulation induced ovarian cancer cell invasion." (PMID 26356564, 2015). "Carboplatin/olaparib plus AVB-500, a selective inhibitor of GAS6-AXL, can increase DNA damage and RAD51 focus formation and slow replication fork progression, resulting in rapid death of ovarian cancer cells in vitro and decreased tumor burden in vivo." (PMID 38539161, 2024). "The GAS6/AXL pathway also confers resistance through interactions with other signaling pathways, such as the PI3K, JAK/STAT and MAPK pathways, in ovarian cancer." (PMID 38539161, 2024). "Inhibition of GAS6/AXL axis reduces RAD51 foci and increase 53BP1 foci, inhibiting homologous recombination (HR) and increasing the sensitivity of ovarian cancer to carboplatin." (PMID 37328828, 2023).
ovarian carcinoma (continued). "Preliminary data indicated that NTNG1 bound GAS6/AXL to activate the Akt pathway, thereby modulating the response of ovarian cancer cells to cisplatin." (PMID 34277602, 2021). "Bioinformatic analyses of the GSE45553 and GSE73935 datasets indicated that NTNG1 was a candidate gene involved in cisplatin resistance in ovarian cancer; the BioGRID demonstrated an interaction between NTNG1 and GAS6." (PMID 34277602, 2021). "Some study suggested that Twist promotes platinum resistance in ovarian cancer via activation of collagen type XI alpha 1 (COL11A1), GAS6, L1CAM, and Akt signaling." (PMID 33076245, 2020). "This study investigated the expression levels of AXL, GAS6, Claudin-1, and Cofilin-1, as genes involved in EMT in relation to clinicopathologic features in ovarian cancer patients." (PMID 31700829, 2019). "In accord with what is observed for ovarian cancer cell lines, in HGEOC patient-derived spheroids, Gas6 induced a stellate invasive phenotype." (PMID 26356564, 2015). "In this report, we unravel a novel signaling cascade induced upon Gas6 stimulation of HGEOC cells, whereby the Gas6/Axl axis, through a crosstalk with the integrin adaptor p130Cas, induces the invasion in Matrigel of ovarian cancer spheroids from cell lines and HGEOC patient-derived cells." (PMID 26356564, 2015). "In ovarian cancer cell lines derived from mesenchymal (Mes) or epithelial (Epi-A) mouse models, Gas6-stimulated Axl-RTK crosstalk in Mes cells, whereas Gas6-induced Axl activation did not involve other RTKs in Epi-A cells." (PMID 32352034, 2020).
Sepsis (26 papers, 2007 to 2025). Sepsis is defined as life-threatening organ dysfunction caused by a dysregulated host response to infection. "Two studies involving critically ill patients admitted to ICUs with sepsis or septic shock showed that Gas6 and Mer were associated with increased mortality." (PMID 35203408, 2022). "A clinical study in sepsis patients reported that elevated Gas6 levels were associated with increased mortality." (PMID 35634305, 2022). "Here, we demonstrated the protective effects of Gas6 on multi-organ dysfunction syndrome (MODS) in sepsis and the underlying mechanisms." (PMID 31263416, 2019). "First, because Gas6, via Akt, causes an increase in the antiapoptotic protein Bcl-2, it is tempting to link the delayed neutrophil apoptosis observed during sepsis with the concentration of this protein." (PMID 17241453, 2007). "To determine whether Gas6 ameliorated vascular hyperpermeability caused by sepsis, we performed an Evans blue dye extravasation assay." (PMID 31263416, 2019). "Studies have found that plasma GAS6 concentrations are elevated in patients with sepsis and septic shock, positively correlating with disease severity." (PMID 40872581, 2025). "Future studies should incorporate clinical patient samples to explore the regulatory effects of the GAS6/AXL signaling pathway in different sepsis conditions and conduct relevant clinical trials to assess its therapeutic potential." (PMID 40480981, 2025). "Although soluble AxL levels increase concurrently, believed to inhibit Gas6 activity by binding with it, the upregulation of Gas6 during sepsis exceeds that of sAxl." (PMID 38956732, 2024). "GAS6 is a protein‐coding gene, and elevated levels of plasma GAS6 are found in numerous pathological conditions, including sepsis, obesity, chronic renal disease, cardiac hypertrophy, and systemic lupus erythematosus." (PMID 38872467, 2024). "GAS6 is a ligand of the receptor tyrosine kinase Axl and its blood levels are elevated in inflammatory conditions, such as sepsis and SLE." (PMID 37194071, 2023). "Axl can also be activated by its extracellular ligand, growth arrest specific 6 (Gas6), which is increased in sepsis in the blood and is suggested to play a role in systemic inflammation." (PMID 35634305, 2022). "Soluble tyrosine kinase receptor Mer (sMer) and its ligand Growth arrest-specific protein 6 (Gas6) are predictors of mortality in patients with sepsis." (PMID 35203408, 2022). "AKI is very frequent (28% in our cohort) in patients with sepsis and septic shock, and we found higher plasma levels of Gas6 and sMer in these patients." (PMID 35203408, 2022). "Higher plasma levels of Gas6 were also found in critically ill patients with sepsis who developed lung injury." (PMID 35203408, 2022). "Recently, the role of the tyrosine kinase receptor Mer and its ligand growth arrest-specific 6 protein (Gas6) has emerged as an important contributor to the inflammatory response in patients with sepsis, especially in the ICU." (PMID 35203408, 2022). "The Gas6 plasma concentration was significantly lower in patients with RTI-r sepsis (29.8 [22.3–40.0] vs. 33.6 [24.8–46.8] ng/mL, p < 0.001), while sMer was not different in the two groups (8.3 [4.0–14.4] vs. 8.2 [3.9–14.8] ng/mL, p = 0.75)." (PMID 35203408, 2022). "Even if our results showed a lower plasma concentration of Gas6 in patients with RTI-r sepsis, more sick patients with PaO2/FiO2 ≤ 300 had slightly higher levels of Gas6." (PMID 35203408, 2022). "More than ten years ago, the groups of Borgel and Gibot investigated for the first time the role of TAM and their ligands as biomarkers in septic patients, noticing a significant correlation between Gas6 and sepsis." (PMID 33803290, 2021). "Several studies confirm an elevated concentration of Gas6 in patients with sepsis, often with a strong correlation with the number of failing organs or organ damage score." (PMID 34836355, 2021).
Sepsis (continued). "This study has several limitations, since further analyses are clearly needed to better understand and characterize the role of Gas6 and its mechanisms in a complex disease, such as sepsis and sepsis-induced organ damage." (PMID 33803290, 2021). "Taken together, these observations suggest that Gas6 administration ameliorates sepsis-driven organ damage and that this effect is likely mediated by parenchymal cells rather than hematopoietic cells." (PMID 33803290, 2021). "TAM receptors are activated upon binding to several ligands, among which growth arrest-specific 6 (Gas6) is a vitamin K-dependent protein normally circulating in the bloodstream found at increased plasma concentration during sepsis." (PMID 33803290, 2021). "In this study, we investigated the possible therapeutic efficacy of Gas6 administration following antibiotic therapy in a murine model of sepsis." (PMID 33803290, 2021). "Analogously, Ekman and colleagues, some years later, observed a correlation between Gas6 and the degree of organ damage in sepsis." (PMID 33803290, 2021). "Even though the immunomodulatory function of TAM receptors is well established in multiple systems, an important role of Gas6 in attenuating sepsis-induced tight junction injury and vascular endothelial hyperpermeability in vivo has only recently emerged." (PMID 33803290, 2021). "Gas6‐/‐ mice were injected with TNF‐α to investigate sepsis and transplantation‐induced organ destruction, considering the organismic influence brought on by gas6 knockout, it is hard to attribute this effect to endothelial cells alone." (PMID 32462812, 2020). "Regarding the focus of this review, we still know little about the response of TAM receptors and Gas6 in a murine sepsis model." (PMID 31485279, 2019). "Taken together, this study suggests that Gas6 has a protective effect on MODS in sepsis by inhibiting the vascular endothelial hyperpermeability and alteration of tight junction and that the Axl/NF-κB signaling pathway underlies these effects." (PMID 31263416, 2019). "In line with our findings, some studies have shown that Gas6 can effectively reduce organ injury in sepsis." (PMID 31263416, 2019). "In this narrative review, we highlight the current knowledge as well as the last discoveries on TAM and Gas6 implication in different clinical conditions, notably in sepsis and septic shock." (PMID 31485279, 2019). "The therapeutic role of Gas6 has been suggested also by two other research groups using mouse models of sepsis-induced kidney injury and sepsis-induced lung injury." (PMID 31485279, 2019). "In our study, we first reported that the protective role of Gas6 on sepsis-induced MODS was related to the vascular endothelial permeability." (PMID 31263416, 2019). "Previous studies demonstrated that Gas6 exerted protective effects in sepsis-induced acute kidney injury and acute lung injury in mice." (PMID 31263416, 2019). "We investigated Gas6-ameliorated MODS by inhibiting vascular endothelial hyperpermeability in a mouse model of sepsis." (PMID 31263416, 2019). "Plasma Gas6 levels are elevated in humans with inflammatory conditions, including sepsis and correlate with organ dysfunction and disease severity." (PMID 27788141, 2016). "In contrast to the current study, results from previous studies have shown that circulating Gas6 levels are higher in medical conditions of chronic inflammation, such as chronic renal failure, sepsis, and lupus disease." (PMID 24236135, 2013). "The patients with severe sepsis had significantly increased Gas6 concentrations when compared to the sepsis group." (PMID 20731857, 2010). "In this study, we have determined the Gas6 and sAxl concentrations in a large number of patients with sepsis and related inflammatory conditions." (PMID 20731857, 2010).
Sepsis (continued). "The relative increase in Gas6 concentration in the patients is higher than that of sAxl, suggesting that increased Gas6-mediated cellular signaling occurs during sepsis, but it remains to be determined in which cells the increased signaling occurs." (PMID 20731857, 2010). "Due to the large increase of Gas6, Gas6 induced signaling is presumably increased during sepsis and related inflammatory conditions." (PMID 20731857, 2010). "Our data support the previous reports of increased Gas6 during sepsis, and we find correlations between Gas6 or sAxl concentrations and degree of organ damage." (PMID 20731857, 2010). "sAxl is also increased, but it does not follow the two-fold increase observed for Gas6, indicating increased Gas6 signalling during sepsis and related inflammatory conditions." (PMID 20731857, 2010). "• Gas6 plasma concentrations are increased in patients with sepsis, SIRS and infections compared to controls." (PMID 20731857, 2010). "When evaluating the severe sepsis and sepsis groups separately, Gas6 correlated to IL-6, bilirubin, INR, procalcitonin and number of failing organs." (PMID 20731857, 2010). "We can confirm results of earlier studies showing that circulating Gas6 is increased in sepsis and related syndromes." (PMID 20731857, 2010). "The aim of this study was to investigate the Gas6 and sAxl concentrations in plasma in a large cohort of patients with sepsis and related inflammatory syndromes." (PMID 20731857, 2010). "A positive correlation (Spearman rank-order coefficient [rs] = 0.37, P = 0.01) was found between Gas6 level and Sepsis-related Organ Failure Assessment score." (PMID 17241453, 2007). "However, in sepsis, the concentration of sAXL increases in patients, while the concentration of Gas6 remains relatively unchanged." (PMID 40933570, 2025). "Elevated levels of Gas6 have been observed in patients with severe sepsis." (PMID 38956732, 2024). "As growth arrest-specific gene 6 (Gas6)/Tyro3, Axl, MerTK (TAM) receptors signaling has shown immunomodulatory activity in sepsis, here we sought to determine whether Gas6 protein injection could mitigate MOF in a cecal slurry mouse model of sepsis." (PMID 33803290, 2021). "Thus, systemic administration of Gas6 is able to induce a response against sepsis not only from myeloid cells, either resident or recruited from the bloodstream, as one would expect, but also from parenchymal cells." (PMID 33803290, 2021). "Thus, our findings appear to indicate a protective role of Gas6 also in sepsis-induced kidney injury." (PMID 33803290, 2021). "Thus, here we sought to determine the biological role of the Gas6/TAM axis in a mouse model of sepsis following broad-spectrum antibiotic administration." (PMID 33803290, 2021). "Furthermore, the expression of Gas6 appears to be stimulated by an inflammatory response, since elevated serum Gas6 levels were shown in sepsis and other systemic inflammation." (PMID 32958023, 2020). "Hence, these studies suggest a possible role of Gas6 in tuning the immune response during sepsis by linking the innate and adaptive immune system." (PMID 31485279, 2019). "In conclusion, our results demonstrated that Gas6 ameliorated sepsis-induced MODS." (PMID 31263416, 2019). "In fact, many studies have investigated the effect of Gas6 on sepsis." (PMID 31263416, 2019). "Furthermore, Gas6 came out as an early predictor of mortality and was able to identify some life-threatening sepsis complications." (PMID 31485279, 2019). "Therefore, also in sepsis, where Gas6 levels are high, the injection of exogenous Gas6 seems to improve the outcome." (PMID 31485279, 2019). "Gas6 was present at high levels in plasma during sepsis and correlated well with organ dysfunction." (PMID 31263416, 2019). "Gas6 attenuates the systemic inflammatory response in the early phase of sepsis." (PMID 27788141, 2016). "It seems that Gas6 plasma level within 24 hours of ICU admission may predicts in-ICU mortality in patients with sepsis." (PMID 27788141, 2016).